IL10 (interleukin 10)
Diseases named in the same sentence as IL10 in open-access papers (continued):
Sharing a sentence is not in itself a finding about the gene and the disease.
hepatitis B (26 papers, 2013 to 2025). "IL-10 is an immunoregulatory cytokine and its levels were previously reported to be closely associated with disease progression and outcomes in both hepatitis B and vivax malaria." (PMID 31233500, 2019). "For example, IL-10 and 28B, which are important risk factors for hepatitis B virus infection may also be associated with CP." (PMID 30755190, 2019). "A similar role for IL-10 producing NK cells was described in patients with chronic viral infections, such as hepatitis B and C." (PMID 39355242, 2024). "IL-10 combined with the Chinese Severe Hepatitis B Study Group-ACLF II score (COSH-ACLF IIs) had excellent performance in predicting 28- and 90-day mortality (AUCs: 0.848 and 0.823, respectively)." (PMID 37822472, 2023). "Here, KCs produce IL10 upon TLR2 activation in response to hepatitis B antigens, and the elevated IL10 inhibits CD8 T cell function in HBV carrier mice." (PMID 32632817, 2021). "In chronic viral infections such as hepatitis B, elevation of IL-10 was found to coincide with disease flares and in vitro blockade of IL-10 was found to enhance polyfunctional antiviral responses in CD8+ T cells." (PMID 24040431, 2013). "The single most relevance of this study and proof of principle are demonstrated in acute and chronic infection in human Hepatitis B where we found that iCa2+ influx in CD8+ T cells was completely abrogated with a significant increase in IL-10 and decrease in IFN-γ." (PMID 32210950, 2020). "Allele C and genotype CC at IL10 rs1800871 loci, as well as allele T and genotype TT at TLR rs3775291 loci, may increase susceptibility to Hepatitis B infection." (PMID 32912361, 2020). "The role of IL-10 in the pathogenesis of Hepatitis-B is paradoxical where some authors report that effector CD8+ T cell-derived IL-10 enhances acute liver immunopathology whereas some others report; IL-10 mediated liver immunopathology during chronic Hep-B infection in Indian population." (PMID 32210950, 2020). "Not coincidentally, in an analysis of the immune response to hepatitis B virus infection, it was found that patients who recovered from acute hepatitis B virus infection activated the Th2 release of IL-4 and IL-10, which induced the B-cell production of antibodies." (PMID 26824828, 2016). "In light of this finding, we evaluated IFN-γ, IL-5, and or IL-10 production in whole blood cultures in response to HbsAg stimulation before and after hepatitis B immunization and also analyzed if cytokine production was associated with antibody responses to the immunizations." (PMID 27926921, 2016). "In addition to T cells, IL-10-producing regulatory B cells and the serum IL-10 level tended to increase in parallel with the rising serum HBV DNA during the acute flare of hepatitis B, and began to decrease soon after the peak of serum ALT level during the flare." (PMID 35163330, 2022). "Notwithstanding the increased IL-10 level in hepatitis B patients, we observed high-level IL-23 expression and Th17 frequency in these patients, suggesting that other mechanisms likely exist to support Th17 function by antagonizing the suppressive effects of IL-10 during HBV infection in vivo." (PMID 23825942, 2013). "We also found that incidence of hepatitis B was positively correlated with IFN-α, and negatively correlated with transforming growth factor-beta (TGF-β) and interleukin- 10 (IL-10)." (PMID 35603222, 2022). "IL-10 is elevated during HIV, hepatitis C virus, and hepatitis B virus infections." (PMID 30914509, 2019). "The diminished release of IL-10 was also reported in hepatitis B vaccination nonresponders." (PMID 24598061, 2014). "IL-10, a prototype of type-2 cytokine, is considered an anti-inflammatory cytokine and has inhibitory effect on immune response,whereas IFN-γ, a type-1 cytokine, is significantly increased in patients with acute hepatitis B, which would eventually eliminated viral from hepatocytes." (PMID 25144199, 2014).
hepatitis B (continued). "These cells can suppress immune responses by altering the microenvironment of cytokines, which may in turn inhibit the production of antibodies against hepatitis B. Hepatitis B vaccine nonresponders with elevated levels of IL-10 have a higher frequency of CD24highCD38high Bregs." (PMID 40181820, 2025).
Peri-Implantitis (26 papers, 2015 to 2025). An inflammatory process with loss of supporting bone in the tissues surrounding functioning DENTAL IMPLANTS. "The subgroup of studies focusing on cytokine polymorphisms (IL-1A, IL-1B, IL-10, IL-17A) demonstrated variable associations with peri-implantitis risk." (PMID 41373620, 2025). "Interleukin-10 genotypes are also associated with peri-implantitis, mainly with hindered IL-10 anti-inflammatory response." (PMID 37232785, 2023). "First and foremost is the IL-10 (+1082) genotype, which is considered to be associated with peri-implantitis development." (PMID 37232785, 2023). "Cytokine levels in PICF were markedly elevated in peri-implantitis cases: IL-6 (235.56 ± 56.34 pg/mL vs. 22.88 ± 8.06 pg/mL), IL-10 (73.13 ± 15.11 pg/mL vs. 13.13 ± 4.25 pg/mL), and TNF-α (148.94 ± 53.99 pg/mL vs. 8.31 ± 2.89 pg/mL)." (PMID 40959363, 2025). "Our findings are in line with the studies in which IL-10 levels were found higher in the presence of peri-implantitis than in healthy controls." (PMID 39080143, 2024). "The results of several studies comparing IL-10 levels in peri-implantitis and healthy peri-implant tissues have been contradictory." (PMID 39080143, 2024). "Collectively, these results suggest that the lower IL-10 levels in peri-implantitis individuals result in higher IL-6 cytokines levels potentially promoting a destructive inflammatory response around dental implants." (PMID 37355561, 2023). "Comparing mucositis and peri-implantitis, three studies showed higher IL-1β levels and lower levels of IL-10 in peri-implantitis individuals." (PMID 37355561, 2023). "Higher levels of IL-6 and lower levels of IL-10 were found in peri-implantitis individuals in comparison to mucositis and healthy individuals." (PMID 37355561, 2023). "Comparing mucositis and peri-implantitis, three studies were included and showed lower levels of IL-10 in peri-implantitis subjects." (PMID 37355561, 2023). "Three studies also showed higher IL-6 and IL-10 levels in PICF of individuals with peri-implantitis in comparison with healthy individuals." (PMID 37355561, 2023). "Contrariwise, two studies observed higher IL-6 levels and lower levels of IL-10 in peri-implantitis in comparison to healthy individuals." (PMID 37355561, 2023). "One study showed higher IL-1β levels and lower levels of IL-10 in individuals with mucositis and peri-implantitis in comparison to healthy." (PMID 37355561, 2023). "The IL-1β/ IL-10 ratio was found to be 9.9 ± 11.9 for the healthy group and 37.2 ± 44.4 for the peri-implantitis group (p = 0.006)." (PMID 25888355, 2015). "Furthermore, the simultaneous increase in TNF-α and VEGF was identified as a potential contributor to the heightened inflammatory response in peri-implantitis, a response that appeared to be counterbalanced by the elevated levels of IL-10." (PMID 38477721, 2024). "Other cytokines found in peri-implantitis include IL-4, IL-6,IL-8, IL-10, IL-12, and IL-17." (PMID 39195095, 2024). "Interestingly, when comparing peri-implantitis with peri-implant mucositis, the former presented higher concentrations of IL-10 in tissues surrounding implants." (PMID 37232785, 2023). "A local increase in proinflammatory cytokines (e.g., IL-6 and IL-10) in the crevicular fluid has been reported for peri-implantitis, which may plausibly have systemic effects." (PMID 34054959, 2021). "However, induction of peri-implantitis elevated the expression level of IL10 (DM+lig vs. DM), whereas glycemic control markedly enhanced such increase of IL10 mRNA expression (DM+lig+BG control vs. DM+lig)." (PMID 34401982, 2021). "But some studies reported that IL-10 increases in peri-implantitis." (PMID 33376734, 2020). "Concentrations of IL-10, which is an anti-inflammatory cytokine, decrease in peri-implantitis." (PMID 33376734, 2020).
Peri-Implantitis (continued). "In our study, the significant time-dependent decrease in PICF IL-10 levels after the treatments may be interpreted as the resolution of inflammation with peri-implantitis treatment and thus the decrease in anti-inflammatory as well as pro-inflammatory cytokines in the region." (PMID 39080143, 2024). "Similarly, peri-implantitis may influence the systemic status through inflammatory cytokines such as IL-1, IL-6, and IL-10 and matrix metalloproteinases." (PMID 34054959, 2021). "The aim was to evaluate the association between single-nucleotide polymorphisms (SNPs) in genes involved in inflammation and bone metabolism (BMP-4, BRINP3, CD14, FGF-3, FGF-10, GBP-1, IL-1α, IL-1β, IL-10, LTF, OPG, and RANKL) and peri-implantitis." (PMID 41373620, 2025). "This prospective cross-sectional study demonstrated that IL-6, IL-10, and TNF-α levels in PICF were significantly elevated in periodontally healthy patients with peri-implantitis compared to those with healthy-periodontal implants." (PMID 40959363, 2025). "The PI, probing depth, and IL-6, IL-10, and TNF-α levels were significantly higher in the peri-implantitis group, with large effect sizes indicating substantial biological differences between the groups." (PMID 40959363, 2025). "The selection of IL-6, IL-10, and TNF-α in this study was driven by their controversial roles in peri-implantitis." (PMID 40959363, 2025). "The results of this study provide significant insights into the roles of IL-6, IL-10, and TNF-α in peri-implantitis, addressing their controversial status as biomarkers." (PMID 40959363, 2025). "The significant elevations in IL-6, IL-10, and TNF-α levels in the peri-implantitis group compared to those in the healthy implant group, as observed in this study, can be attributed to the heightened inflammatory response characteristic of peri-implantitis." (PMID 40959363, 2025). "This study, for the first time demonstrates the balance of HIF-1α, TNFα, IL-10, and VEGF in peri-implantitis." (PMID 38477721, 2024). "Although the present study was the first to assess the TNF-α, IL-10, VEGF, and HIF1-α immune balance in peri-implantitis, it has limitations since we evaluated the local immune response of the peri-implant condition at a given time." (PMID 38477721, 2024). "Logistic regression analysis revealed that smoking, PI, and probing depth were significant predictors of peri-implantitis, while IL-10 and TNF-α exhibited a positive and slight negative association, respectively." (PMID 40959363, 2025). "This study aimed to compare the levels of HIF1-α, VEGF, TNF-α, and IL-10 in the peri-implant crevicular fluid of patients with and without peri-implantitis." (PMID 38477721, 2024). "TNF-α revealed significant positive correlations with IL-10 (p=0.0008) and VEGF (p=0.0246), whereas HIF-1α and IL-10 levels (p=0.0041) demonstrated a negative and significative correlation in the peri-implantitis group." (PMID 38477721, 2024). "Considering these findings, we hypothesized peri-implantitis increases the expression of VEGF, HIF-1α, TNF-α, and IL-10 in the PICF." (PMID 38477721, 2024). "The authors compared the levels of HIF1-α, VEGF, TNF-α, and IL-10 in peri-implant crevicular fluid between patients with or without peri-implantitis." (PMID 38477721, 2024). "However, it is crucial to acknowledge that this study represents the first attempt to correlate TNF-α, IL-10, VEGF, and HIF1-α in peri-implantitis." (PMID 38477721, 2024). "This study investigated the roles of interleukin-6 (IL-6), interleukin-10 (IL-10), and tumor necrosis factor-alpha (TNF-α) in peri-implantitis by comparing their levels in peri-implant crevicular fluid (PICF) between healthy implants and peri-implantitis groups." (PMID 40959363, 2025).
Peri-Implantitis (continued). "During the treatment of peri-implant mucositis and peri-implantitis there were minimal effects of non-surgical treatment alone on the investigated inflammatory biomarkers (IL-4, IL-10, and IL-12, TNF-a, RANKL, OPG IL-1β, IL-6, TNF-α, MCP-1/CCL2, MIP-1α/CCL3, IFN-γ, MMP-8, sRANKL, OPG and G-CSF)." (PMID 36360962, 2022). "IL-1β (p < 0.01), IL-6 (p < 0.01), IL-10 (p < 0.05) and TNF-α (p < 0.01) are significantly higher at the sites with peri-implantitis compared to healthy peri-implant tissue, while IL-8 did not increase significantly." (PMID 25888355, 2015). "In this study, it was found that IL-1β (p < 0.01), IL-6 (p < 0.01), IL-10 (p < 0.05) and TNF-α (p < 0.01) were significantly increased at the sites with peri-implantitis, while IL-8 was not." (PMID 25888355, 2015). "The results showed that the levels of IL-1β, IL-6, IL-10, and RANKL/OPG are not balanced in peri-implant disease, suggesting that these mediators are involved in the host osteo-immunoinflammatory response related to peri-implantitis." (PMID 37355561, 2023).
cardiomyopathy (25 papers, 2012 to 2026). A disease of the heart muscle or myocardium proper. "A balance between host and parasite in asymptomatic cases may be maintained by expression of the anti-inflammatory cytokine IL-10, while cardiomyopathy is associated with inflammation triggered by IFN-gamma and TNF-alpha." (PMID 29281643, 2017). "Moreover, IL-10 null mice did not exhibited severely reduced muscle strength due to severe inflammation, while older IL-10-deficient mdx mice presented with abnormal cardiac function that shared several characteristics with DMD-associated cardiomyopathy." (PMID 29259687, 2016). "The progressive destructive process in patients with cardiomyopathy could therefore be the result of a decrease in the regulatory activity of the pathogenic Th1 response due to a decrease in IL-10 production." (PMID 24603474, 2014). "Moreover, the low proportion of regulatory T cells observed in the CCC group may highlight the deficiency of IL-10-producing cells typical of the immunological imbalance leading to cardiomyopathy development." (PMID 36558736, 2022). "Patients with indeterminate disease retain a balancedDN γδ phenotype, coexpressing IFN-γ and IL-10, whilethose with cardiomyopathy exhibit an IFN-γ-dominant profileassociated with worse cardiac function." (PMID 41365681, 2026). "Beta-blockers are shown to effectively suppress inflammatory molecules, such as TNFα and IL10 in cardiomyopathy patients." (PMID 38216681, 2024). "They observed the production of IFN-γ by CD3+ CD4+ cells in cardiomyopathy, along with the production of IL-10 by macrophages/monocytes, leading to regulation of the immune response, in indeterminate patients." (PMID 38133693, 2023). "Overall, this study revealed the downregulation of FXR and IL-10/IL-10R-related serological, functional and pathogenic signalling mechanisms, and phenotypic abnormalities of NASH-related cardiomyopathy at systemic and cellular levels in a mouse model." (PMID 36490253, 2022). "Previously, we demonstrated that CCD patients with cardiomyopathy show changes in the ex vivo Breg cell phenotypic distribution although maintain IL-10 production capacity." (PMID 34458163, 2021). "Higher frequencies of CD4+ IL-17A+ T-cells, lower levels of IL10 and IL10, and higher levels of IFNγ and TNFα are observed in individuals with more severe cardiomyopathy." (PMID 33193300, 2020). "So, the genetic control of the human susceptibility to cardiomyopathy mainly target genes that are involved in the regulation of this TH1 response, such as IL12B and IL10 genes." (PMID 32733459, 2020). "IL-10 is a crucial regulatory cytokine, and its production is associated with a better outcome of chronic Chagas disease, since asymptomatic individuals were found to produce higher IL-10 levels than patients with cardiomyopathy." (PMID 31244833, 2019). "In contrast, cells from free/mild cardiomyopathy patients produced higher amounts of IL-10 than cells from moderate/severe cardiomyopathy patients group." (PMID 22545173, 2012). "For the IL10 gene, the rs3024496 polymorphism (located in the 3′UTR region), and rs1800896 polymorphism (located in the promoter region) have shown trends of association to susceptibility to cardiomyopathy." (PMID 32733459, 2020). "Moreover, patients with less aggressive forms of the disease (cardiomyopathy free or mild cardiomyopathy individuals) produce higher levels of the cytokines IL-10 and IL-17." (PMID 22545173, 2012). "Among studied cytokines, some were associated with general susceptibility to T. cruzi infection (IFN-γ, MIF, IL-4, TNF, TGF-β, and IL-18) and others with cardiomyopathy development (TNF, IL-1, BAT1, MCP-1, LT-α, IL-12, and IL-10)." (PMID 29670670, 2018). "Cultures of PBMC from patients with moderate and severe cardiomyopathy produced high levels of TNF-α, IFN-γ and low levels of IL-10, when compared to mild cardiomyopathy or cardiomyopathy-free patients." (PMID 22545173, 2012).
cardiomyopathy (continued). "Our data confirmed that PBMC from the group of moderate/severe cardiomyopathy patients produce more IFN-γ and TNF-α and less IL-10 than the cells obtained from the other groups." (PMID 22545173, 2012). "Here, we studied the proportion of different B cell subsets and their capacity to secrete IL-10 ex vivo in peripheral blood from patients with or without CCD cardiomyopathy." (PMID 33750870, 2021). "The low production of polyfunctional T cells in patients with severe cardiomyopathy was not due to enhanced IL-27-induced IL-10 production, but in contrast, IL-10 was only induced in CD4+ T cells of the G0 subject group and in uninfected subjects." (PMID 34061845, 2021). "In vitro treatment of PBMCs with IL-27 and IL-7 improved monofunctional and polyfunctional Th1 responses, accompanied by the induction of IL-10 and Bcl-2 expression in subjects without heart disease but did not improve those in subjects with cardiomyopathy." (PMID 34061845, 2021). "Systemic cytokine levels were low (IL-6 and IL-10) or undetectable (TNF-α) with or without induction of takotsubo-like cardiomyopathy." (PMID 30623136, 2018). "The cultures of PBMC from patients with moderate/severe cardiomyopathy produced higher IFN-γ and TNF-α, and lower IL-10 levels than those observed in PBMC culture from free/mild cardiomyopathy patients, which is in accordance with previous reports by other researchers." (PMID 22545173, 2012). "Isolated B cells from CCD patients with or without cardiomyopathy and non-infected (NI) donors were stimulated with T. cruzi lysate or CpG + CD40L, and characterized by flow cytometry based on the expression of CD24, CD27, CD38, and the regulatory molecules IL-10 and PD-L1." (PMID 34458163, 2021). "Moreover, other SNP related to other cytokines that could be related to susceptibility to T. cruzi infection (IFN-γ, MIF, IL-4, TNF, TGF-β, and IL-18) or cardiomyopathy development (TNF, IL-1, BAT1, MCP-1, LT-α, IL-12, and IL-10) were not studied." (PMID 29670670, 2018).